IL6 (interleukin 6)
Diseases named in the same sentence as IL6 in open-access papers (continued):
Sharing a sentence is not in itself a finding about the gene and the disease.
non-proliferative diabetic retinopathy (5 papers, 2012 to 2025). Early stage diabetic retinopathy, characterized by the absence of neovascularisation of the retina. "Indeed, IL-6 has been implicated in the breakdown of the blood-retinal barrier, which may contribute to the pathogenesis of earlier stages of nonproliferative diabetic retinopathy." (PMID 22511846, 2012).
ocular infection (5 papers, 2013 to 2025). "Thus, in contrast to direct intranasal or ocular infection where cytokines such as IL-1, IL-6, IFN-ß or TNF-α were strongly altered, stimulation in our environment of interest apparently was not sufficient to provoke a similar response." (PMID 29077773, 2017). "Although IL-6 is protective against lethal HSV-1 ocular infection, elevated levels may be neurotoxic and also increase the permeability of the BBB." (PMID 24068938, 2013).
ovarian endometriosis (5 papers, 2019 to 2025). A non-neoplastic disorder characterized by the growth of endometrial tissue in the ovaries. "We performed analyses of the mRNA and protein expression of IL-6 in ovarian endometriosis." (PMID 41227338, 2025). "The results showed that IL-6 drives inflammation in conditions of PCOS and ovarian endometriosis, which then disrupts ovulation and embryo implantation." (PMID 41227338, 2025). "However, a comprehensive assessment of plasma, peritoneal fluid, and endometrioma TNF-α, IL-6, and IL-8 concentrations in women with ovarian endometriosis has not yet been performed." (PMID 40507929, 2025).
overactive bladder (5 papers, 2013 to 2025). Symptom of overactive detrusor muscle of the urinary bladder that contracts with abnormally high frequency and urgency. "The cytokines with high diagnostic values to distinguish IC/BPS and overactive bladder included IL-10, RANTES, eotaxin, CXCL10, IL-12p70, NGF, IL-6, IL-17A, MCP-1, and IL-1RA." (PMID 35626252, 2022). "The oxidative stress markers and proinflammatory cytokines including IL-8-like cytokine CXCL1/CINC-1, TNF-α, and IL-6 were significantly higher in the atherosclerotic ischemic rats; these markers could be key factors in the development of bladder overactivity." (PMID 24098552, 2013). "Increased responsive proinflammatory mediators (NGF, ICAM-1, COX-2, IL-1β, IL-6, TNF-α) likely contribute to bladder overactivity." (PMID 39941129, 2025). "Using different urinary biomarkers including IL-10, RANTES, eotaxin, CXCL10, IL-12p70, NGF, IL-6, IL-17A, MCP-1, and IL-1RA, IC/BPS could be distinguished from overactive bladder." (PMID 36233356, 2022).
periapical granuloma (5 papers, 2018 to 2024). Chronic nonsuppurative inflammation of periapical tissue resulting from irritation following pulp disease or endodontic treatment. "There is extensive research with inflammatory markers (e.g., Galectin 1 and 7, intercellular adhesion molecular-1, degranulated mast cells, TGFb, IFNd, TNFa, IL4, IL6), observing differences in expression between periapical cysts and periapical granulomas." (PMID 39691380, 2024). "Compared to healthy control, the expression of SARS-CoV-2 receptors and IL-6 in periapical granuloma remained significantly lower and higher, respectively." (PMID 34749700, 2021). "The pro-inflammatory characteristic of periapical granulomas has been established; increased IL-1β, IL-6 and TNF-α has been documented in symptomatic APs versus asymptomatic APs." (PMID 35053012, 2021). "The pro-inflammatory characteristic of periapical granulomas has been established; increased IL-1β, IL-6 and TNF-α has been documented." (PMID 35053012, 2021). "Furthermore, IL-6 gene expression was significantly upregulated in the periapical abscess (P < 0.001), radicular cyst, and periapical granuloma (P < 0.0001) when compared with healthy controls." (PMID 34539639, 2021).
periventricular leukomalacia (5 papers, 2012 to 2023). Periventricular leukomalacia (PVL) is a brain injury disorder characterized by the death of the white matter of the brain due to softening of the brain tissue. "Studies have shown that IL-6 is linked to clinical chorioamnionitis and preterm birth and that there is a three-fold increased risk for the development of periventricular leukomalacia (PVL) in preterm infants." (PMID 24903966, 2014). "The involvement of astrocytes in the pathogenesis of WMI is suggested by increased cytokine expression (IL-1β, IL-6, and TNF-α) in both the diffuse and focal components of periventricular leukomalacia (PVL)." (PMID 22530124, 2012).
pneumoconiosis (5 papers, 2009 to 2025). An occupational lung disorder caused by inhalation of dust particles. "Overall, there was a significant association between IL-1RA +2018 and IL-6 -634 with the risk of pneumoconiosis." (PMID 40182855, 2025). "The IL-1RA +2018 variant remarkably increased the pneumoconiosis risk in Asians and Caucasians, while the IL-6 -634 genotype decreased the pneumoconiosis risk among Asians." (PMID 40182855, 2025). "Our results revealed that the frequencies of the IL-6 -634 G alleles in the case and control groups were 25.7 and 35.2%, respectively, and IL-6 -634 was significantly associated with the risk of pneumoconiosis, compared to IL-6 -174." (PMID 40182855, 2025). "In contrast, the IL-6 -634 genotype was associated with a lower risk of pneumoconiosis among Asians." (PMID 40182855, 2025). "In conclusion, the results have provided a comprehensive evidence that the IL-1RA +2018T/C and IL-6 -634C/G polymorphisms were correlated with the risk of pneumoconiosis." (PMID 40182855, 2025). "The IL-6 -634 variant may decrease the pneumoconiosis risk by influencing the expression of IL-6, which provides a biologically plausible description to confirm our results." (PMID 40182855, 2025). "Moreover, we found remarkable association between the IL-6 -634 mutant and pneumoconiosis based on the subgroups of PB, HB, and low and high scores." (PMID 40182855, 2025). "In contrast, the IL-6 -634 variant was significantly correlated with the decreased risk of pneumoconiosis among Asians, suggesting that the IL-6 -634G-allele variant might play a protective role among Asians." (PMID 40182855, 2025). "The association between the IL-6 -634C/G, IL-6 -174G/C, and IL-17A -832A/G gene polymorphisms and pneumoconiosis was examined in 5 studies involving 504 patients and 512 controls, 5 studies involving 660 patients and 848 controls, and 5 studies involving 1,179 patients and 1,235 controls." (PMID 40182855, 2025). "The human IL-6 gene is localized on chromosomes 7p21-24, and certain known loci, including -174 and -634, in its promoter region have been widely studied in pneumoconiosis." (PMID 40182855, 2025). "As we all know, IL-6, as a pro-inflammatory factor, plays an important role in the occurrence and development of pneumoconiosis." (PMID 34349786, 2021).
polyarticular JIA (5 papers, 2018 to 2023). "Over the following years other anti-TNF inhibitors, including adalimumab, infliximab, and golimumab, the IL-6 inhibitor tocilizumab, and costimulatory disruption abatacept were tested in RCTs that included patients with polyarticular JIA." (PMID 37475055, 2023). "IL-6 is a key driver of systemic autoimmune diseases; tocilizumab-mediated IL-6 blockade is effective for children with systemic or polyarticular JIA." (PMID 30547812, 2018).
polycythemia vera (5 papers, 2016 to 2022). "IRAK1 may play a role in MPNs (polycythemia vera [PV], essential thrombocythemia [ET], and myelofibrosis) via inflammatory cytokines, such as IL-6 and IL-8, that are downstream products of the dysregulated NF-κB pathway." (PMID 30279971, 2018). "However, IL-6 and the JAK1/2 inhibitor Ruxolitinib significantly increased angiogenic factors—endothelial nitric oxide synthase (eNOS), VEGF, and hypoxia-inducible factor-1 alpha (HIF-1α)—in patients with polycythemia vera (PV)." (PMID 34206393, 2021).
polymyositis (5 papers, 2012 to 2023). A rare idiopathic inflammatory myopathy characterized by symmetric proximal muscle weakness and elevated muscle enzymes. "There also seems to be elevations of TNF, IL-1 and IL-6 in both DM and polymyositis (PM) patients." (PMID 37681925, 2023).
pustular psoriasis (5 papers, 2020 to 2025). "IL36RN gene mutations are a well-known cause of pustular psoriasis by increasing IL-6 production and offer a chance for target therapy of the skin disease." (PMID 39873967, 2025). "Additionally, IL-6, compared with the other cytokines that are raised in pustular psoriasis, showed the strongest correlation with disease severity and systemic inflammation." (PMID 37631866, 2023).
rhabdomyosarcoma (5 papers, 2017 to 2024). A rare aggressive malignant mesenchymal neoplasm arising from skeletal muscle. "Bazedoxifene showed its anti-tumor activity by inducing apoptosis in rhabdomyosarcoma cells due to IL-6/GP130 signaling inhibition." (PMID 28672024, 2017). "Bazedoxifene also exhibited inhibitory effect on STAT3 activation induced by IL-6 in RH5 rhabdomyosarcoma cells with expressing lower STAT3 phosphorylation and cultured in serum-free medium." (PMID 28672024, 2017). "All these results further validated the inhibitory effects of Bazedoxifene on GP130 mediated STAT3 activation, suggesting the ability of Bazedoxifene to block IL-6/GP130/STAT3 signaling in rhabdomyosarcoma cells." (PMID 28672024, 2017). "Taken together, these findings validate IL-6/GP130 signaling as therapeutic target in rhabdomyosarcoma and provide first evidence that Bazedoxifene may serve as a novel promising drug targeting IL-6/GP130 for treatment of rhabdomyosarcoma." (PMID 28672024, 2017). "In this study, we investigate the effect of Bazedoxifene in rhabdomyosarcoma and evaluate whether inhibiting IL-6/GP130 signaling is an effective therapeutic strategy for rhabdomyosarcoma." (PMID 28672024, 2017). "We also observed overexpression of constitutively active STAT3 protein rescued the cell viability of human rhabdomyosarcoma cells reduced by Bazedoxifene, providing more supportive evidence for the suggestion that Bazedoxifene acts through IL-6/GP130 signaling pathway." (PMID 28672024, 2017). "Therefore, inhibition of IL-6/GP130 signaling may offer new promising strategy for rhabdomyosarcoma therapy." (PMID 28672024, 2017). "As previously discussed, examples such as miR-217 suppressing the carcinogenic IL-6 gene in cardiac myxoma and miR-1 inhibiting c-Met and PAX3 to suppress tumor growth in rhabdomyosarcoma showcase the diverse roles of miRNAs in different tumors." (PMID 38826780, 2024). "The rhabdomyosarcoma (hence called CS3) interactions network numbers 46 nodes, where IL-6 and FGF2 are its most connected nodes." (PMID 34359782, 2021). "Another possible downstream effector of IL-6/GP130, AKT, is also activated in rhabdomyosarcoma and plays an important role in survival and oncogenesis in rhabdomyosarcoma and other types of cancer." (PMID 28672024, 2017). "Bazedoxifene was evaluated for its inhibitory effect on IL-6/GP130/STAT3 signaling in RH30, RD, and RH28 rhabdomyosarcoma cell lines expressing elevated P-STAT3 levels." (PMID 28672024, 2017). "Rhabdomyosarcoma cells showed their sensitivity to GP130 inhibition using gene knockdown or neutralized antibody, suggesting IL-6/GP130 as therapeutic target in rhabdomyosarcoma cells." (PMID 28672024, 2017). "The reason that Bazedoxifene didn’t inhibited P-AKT or P-ERK in all three rhabdomyosarcoma cell lines could be the activation of P-AKT or P-ERK not only depend on IL-6/GP130 signaling, but also depend on the stimulation of others cytokines or growth factor." (PMID 28672024, 2017).
RSV bronchiolitis (5 papers, 2017 to 2026). "However, in preterm infants with RSV bronchiolitis, IL-6 and TNF-α proteins significantly decreased." (PMID 29246125, 2017). "IL-6 and TNF-α mRNA and protein levels in bronchoalveolar lavage fluid in term infants with RSV bronchiolitis were greater than the control group." (PMID 29246125, 2017).
rubella (5 papers, 2010 to 2022). A viral infection caused by the rubella virus. "As expected, FHI patients with rubella had downregulated expressions of bFGF and upregulated expressions of IL-6 and IL-8, similar to that observed in the virus-positive group." (PMID 35178133, 2022). "Since cytokines are important for the development and shaping of innate and adaptive immune responses to rubella, we examined associations between extended haplotypes and rubella virus-specific cytokine (IFN-γ, IL-2, IL-6, TNF-α, and GM-CSF) secretion levels." (PMID 20668555, 2010). "Similar findings were observed for the expressions of IL-6, IL-8, and bFGF in the rubella-positive and rubella-negative groups." (PMID 35178133, 2022). "While the univariate tests implicated SNPs in the LTA, IL6 and IL4R genes, the analysis of all SNPs identified not only these genes but also a broader collection of genes that appear to contribute to variation in rubella antibody levels." (PMID 20923569, 2010).
sacroiliitis (5 papers, 2012 to 2024). "The role of IL-6 was not considered crucial in an animal model of tumour necrosis factor- (TNF-) mediated bilateral sacroiliitis." (PMID 26339141, 2015). "In an animal model of TNF-mediated bilateral sacroiliitis, however, IL-6 was not a crucial regulator of the disease process." (PMID 22404969, 2012).
secondary hemophagocytic lymphohistiocytosis (5 papers, 2021 to 2025). Hemophagocytic lymphohistiocytosis due to infections, autoimmune disorders, or underlying malignancies. "For example, fatal cases of human influenza A H5N1 exhibited elevated IL-6 levels, indicating IL-6-mediated hypercytokinemia, which contributed to reactive hemophagocytic syndrome, multiorgan failure, and ultimately, death." (PMID 40692679, 2025). "Interleukin (IL)-6 is one of the key cytokines in the pathogenesis of secondary hemophagocytic lymphohistiocytosis (sHLH); however, the efficacy and safety of tocilizumab (TCZ), a monoclonal IL-6 receptor antibody, in patients with sHLH is uncertain." (PMID 36131317, 2022).
secondary hyperparathyroidism (5 papers, 2022 to 2025). Overproduction of parathyroid hormone in response to influence external to the parathyroid glands. "This in turn results in secondary hyperparathyroidism, as well as chronic inflammation causing increased production of pro-inflammatory cytokines in the mucosa and serum, particularly TNFα, IL-1, and IL-6 disrupting bone growth and autoimmune factors." (PMID 38049681, 2024). "Elevated serum IL-6 concentration is prevalent in individuals with primary or secondary hyperparathyroidism." (PMID 36299453, 2022). "Paricalcitol treatment was observed to significantly decrease serum levels of IL-6, TNF, and TGF-βin kidney transplant recipients with secondary hyperparathyroidism or proteinuria." (PMID 37483634, 2023).
shigellosis (5 papers, 2011 to 2024). Shigellosis is a bacterial infection leading to dysentery and is caused by Shigella, which are small, ubiquitous Gram-negative bacteria belonging to the enterobacteria family. "In the context of shigellosis, the well-defined histopathology of this animal model mirrors the clinical observation that the IL-6- and IL-8-mediated inflammatory response in shigellosis is localized to the gut." (PMID 22887873, 2012). "It is known that high and sustained local intestinal levels of TNF-α and IL-6 are present during established shigellosis." (PMID 21818362, 2011). "Whereas the sustained elevation of TNF-α and IL-6 in saline treated mice corroborates with the massive tissue damage by the infiltrating monocytes or macrophages, an important characteristic of shigellosis, and ultimate death." (PMID 21818362, 2011). "In a rabbit model of shigellosis, PAMAM-DG prevented epithelial gut wall damage and intestinal villous destruction, reduced local IL-6 and IL-8 expression, and minimized bacterial invasion." (PMID 22887873, 2012).
sinusitis (5 papers, 2018 to 2025). An acute or chronic inflammatory process affecting the mucous membranes of any sinus cavity. "It seems reasonable that LMWH can greatly reduce the inflammatory state of acute sinusitis, which causes the large-scale release of cytokines IL-6 and TNF-α." (PMID 34867331, 2021). "Our data demonstrated that serum levels of IL-6 and TNF-α were significantly increased in nasal packing-induced acute sinusitis rats, which were mainly Th1-related cytokines, and consistent with the pathogenic mechanism of acute sinusitis." (PMID 34867331, 2021). "Furthermore, we investigated the nasal colonization of S. pyogenes, determined cytokine (TNF-α, IL-1β, and IL-6) levels, and conducted a splenocyte proliferative assay in a murine sinusitis model." (PMID 29853978, 2018).
systemic vasculitis (5 papers, 2016 to 2023). "However, our findings are in line with a study on 10 patients with systemic vasculitis, which also observed augmented IL-6 concentrations following TPE." (PMID 37047524, 2023). "Interleukin-6 (IL-6) is one of the key biomarkers and therapeutic target in systemic vasculitis." (PMID 31780858, 2019). "As HSP is the most common systemic vasculitis, overproduction of pro-inflammatory cytokines such as TNF-a, IL-6, and IL-8 may be involved in the disease pathogenesis." (PMID 34277463, 2021).
testicular cancer (5 papers, 2017 to 2022). A primary or metastatic malignant neoplasm that affects the testis. "Previous work revealed a crucial involvement of IL-6 in testis cancer and multifunctionality of TNFα in terms of apoptosis, cell survival, and inflammation." (PMID 35269507, 2022). "Of note, the highest increment of IL6 was observed for the large B-cell lymphoma (FC: 6.39) and testicular cancer (FC: 5.19) whereas IL6 was strongly downregulated in ocular melanomas (FC: −11.90) and breast (FC: −7.37) cancer." (PMID 34576335, 2021). "A pro-proliferative effect of IL6 in testis cancer was suggested, contrasting the outcomes of in vitro treatments of seminiferous tubules in which IL6 was shown to induce normal germ cell apoptosis." (PMID 29250030, 2017). "(see section “Testicular Cancer”), the involvement of IL6 in testis cancer and the suggested immuno-editing by neoplastic germ cells renders this pro-inflammatory and pro-proliferative molecule a putative therapeutic target." (PMID 29250030, 2017). "Most of the studies on testicular cancer have focussed on tumour immunity and have shown that B cells and B-cell-supporting cytokines, such as IL-6 and CXCL-13, are involved in the immunopathology of testicular germ cell neoplasia." (PMID 28900475, 2017). "These experiments attested the pro-inflammatory cytokine IL-6 a major involvement in testis cancer, but the contribution of individual leukocyte subpopulations contained in PBMC is yet unknown." (PMID 35269507, 2022). "Finally, concordant results were achieved for ovarian and testicular cancers in which the rise of IL6 transcript levels corroborates the role of IL-6 in the physiopathology of gonadal tumors." (PMID 34576335, 2021). "Given the cumulative data on the link between IL6 and testis cancer, an experimental immunotherapeutic approach targeting IL6 could provide knowledge of the clinical applicability of these findings." (PMID 29250030, 2017). "IL6 and TNFR2 transcripts were both significantly increased in testis cancer, whereas IL10 and TNFR1 levels remained largely similar to respective controls." (PMID 29250030, 2017).
thrombotic microangiopathy (5 papers, 2020 to 2025). The syndromes of microangiopathic hemolytic anemia, thrombocytopenia, and variable signs of organ impairment, due to platelet aggregation in the microcirculation. "Furthermore, IL-6 can induce a hypercoagulable state with subsequent thrombotic microangiopathy, further impacting kidney function." (PMID 37519535, 2023). "Lastly, the release of IL-6 may at least in part account for the high levels of circulating VWF, but also in the decrease of ADAMTS13 activity, leading to a pro-aggregant phenotype and thrombotic microangiopathy-like features." (PMID 38915768, 2024).